TNF (tumor necrosis factor)
Diseases named in the same sentence as TNF in open-access papers (continued):
Sharing a sentence is not in itself a finding about the gene and the disease.
osteoporosis (continued). "By reducing levels of neuropeptides such as substance P (SP) and calcitonin gene-related peptide (CGRP), as well as inflammatory cytokines like tumor necrosis factor-alpha (TNF-α), bisphosphonates effectively alleviate pain in patients with osteoporosis and improve their overall quality of life." (PMID 41225545, 2025). "Importantly, TNF-alpha has been shown to affect bone mineral density and contribute to the development of osteoporosis." (PMID 41141340, 2025). "The IL-17, HIF-1, and TNF signaling pathways may contribute to curculigoside’s therapeutic effects in osteoporosis." (PMID 40917365, 2025). "Our study is the first to evaluate TNF-α expression in people with osteoporosis and celiac disease." (PMID 41141340, 2025). "associated with SCFAs; upregulated the levels of intestinal acetic, propionic, and valeric acids; and inhibited the expression of serum TNF-α and IL-17 while downregulating the factors related to osteoclast differentiation in bone tissue to alleviate osteoporosis symptoms." (PMID 40741168, 2025). "Consequently, an elevation in pro-inflammatory cytokines such as TNF-α and IL-1β can worsen osteoporosis as they participate in bone turnover and act as potent stimulants of bone resorption." (PMID 40125318, 2025). "Our results for the significantly high IL-1β and TNF-α levels observed in the OVX rats could suggest that olive oil may have an anti-inflammatory effect in OVX-induced osteoporosis." (PMID 40125318, 2025). "IL-10 knockout mice develop osteoporosis and have significantly increased expression of the inflammatory factors IL-6 and TNF in bone, and treatment with E2 ameliorates this process, suggesting that the development of inflammation in bone is closely linked to estrogen deficiency." (PMID 38895114, 2024). "This study demonstrated that TNF‐α regulates the miR‐27a‐3p–Sfrp1 axis in osteoporosis." (PMID 38748896, 2024). "Further evidence demonstrates that blood mononuclear cells with upregulated DANCR expression could lead to osteoporosis, thereby increasing the secretion of IL-6 and TNF-α as well as bone resorbing activity." (PMID 38589566, 2024). "Hence, the immune microenvironment, comprising immune cells and inflammatory factors (IL-1β, IL-18, IL-17, IL-6, and TNF-α), plays a pivotal regulatory role in bone metabolism and contributes to the pathogenesis of osteoporosis." (PMID 38895114, 2024). "Studies have indicated that acupuncture at the ST36 acupoint reduced serum IL-1β expression in ovariectomized rats; generally, acupuncture can mitigate bone destruction and slow the progression of osteoporosis by downregulating inflammatory factors such as tumor necrosis factor-α and interleukin-6." (PMID 39588119, 2024). "Therefore, we focused on the correlation between TNF‐α stimulation and miR‐27a‐3p expression to clarify the role of miR‐27a‐3p in the development of osteoporosis." (PMID 38748896, 2024). "In osteoporosis, cytokines, among osteoclasts and osteoblasts, including Tumor Necrosis Factor (TNF), the interleukin (IL) family, and growth factors (GFs), play crucial roles in bone remodeling, with the RANKL/RANK/OPG axis being essential within the cytokine networks and signaling pathways." (PMID 39200293, 2024). "Dex causes osteoporosis by increasing oxidative stress, decreasing antioxidant markers, reducing bone growth markers (OPG and OCN), and increasing bone turnover and resorption markers (NFATc1, RANKL, ACP, ALP, IL-6, and TNF-α)." (PMID 38247490, 2024). "It was found that the expression of TNF-α in the peripheral blood and local bone tissue of osteoporotic mice was increased in age-related and ovariectomy-induced osteoporosis mouse models, which was positively correlated with the pathological process of osteoporosis." (PMID 38081906, 2023). "Therefore, during the progression of osteoporosis, we found that Atsttrin exhibited its effect through both inhibiting TNFα/TNFR1-mediated inflammation and activating anabolic TNFR2 pathways." (PMID 38081906, 2023).
osteoporosis (continued). "In addition, IL-6 and TNF-α can enhance the bone resorption capacity of PBMCs, stimulate the formation of osteoclasts and contribute to the development of osteoporosis." (PMID 37525169, 2023). "Collectively, osteo-clastogenesis in response to high concentrations of RANKL and TNF-α may explain bone resorption and osteoporosis in patients with HPV infections." (PMID 37113002, 2023). "It is considered, that TNFα (tumor-necrosis factor α) and IL-1 or IL-6 related apoptosis might become a therapeutic target, since osteoporosis exhibits elevated systemic of pro-inflammatory cytokines expression." (PMID 35683288, 2022). "After multivariable adjustment for osteoporosis and fracture-related risk factors, the risk of non-vertebral osteoporotic fractures was not different between users of TNF-α inhibitors (HR 1.07) and csDMARDs." (PMID 35955873, 2022). "However, long-term elevated TNF-α level can also lead to inflammatory-related diseases such as osteoporosis." (PMID 35707276, 2022). "INS, BGLAP, PTH, IGF1, and TNF were the top 5 most studied genes between osteoporosis and DM." (PMID 35719662, 2022). "Decreased physical activity in depressed elderly individuals causes an increase in inflammatory cytokines such as tumor necrosis factor (TNF) and interleukin (IL), further affecting skeletal muscle, reducing muscle density and accelerating the occurrence of osteoporosis." (PMID 35645780, 2022). "A study has hypothesized that there are more TNF-α and IL‐17A producing memory T cells in postmenopausal women with osteoporosis." (PMID 36341399, 2022). "Another mechanism through which MLT can act against osteoporosis is through reversing TNFα effects." (PMID 36371202, 2022). "The association between osteoporosis and postmenopausal state is driven by a decrease in estrogen levels forming bone resorbing cytokines, such as RANKL, TNF-α, and interleukin 1, which can contribute to the onset of a series of diseases including osteopenia and osteoporosis." (PMID 35298563, 2022). "This study showed that TNF-α in the CD group was higher than that in the control group, suggesting that osteoporosis induced by intestinal inflammation may be related to abnormal autoimmune regulation." (PMID 36213271, 2022). "We hypothesized HUCWJCs could be a mediator in osteoporosis therapy and pro-inflammatory factors (TNFα) may inhibit its anti-inflammatory effects." (PMID 35936064, 2022). "TNFα can disrupt osteogenesis and therefore contribute to inflammation-related osteoporosis." (PMID 36371202, 2022). "Furthermore, it been shown that TNF-α inhibits Foxo1 by up-regulating miR-705, aggravating oxidative damage in BMSCs during osteoporosis." (PMID 33610167, 2021). "Biological DMARDs targeting TNF and IL-6 inhibit synovitis and bone and cartilage destruction, but do not influence the risk of osteoporosis." (PMID 33802804, 2021). "Therefore, exploring new pathways to arrest TNF-α-induced cytotoxicity and apoptosis in osteoporosis is necessary." (PMID 34712334, 2021). "Recently, in the study of a rat model of disuse osteoporosis, irisin treatment increases the bone formation rate of unloading hindlimbs and reduce the expression of pro-inflammatory factors such as tumor necrosis factor (TNF)-α and Interleukin (IL)-17." (PMID 34017836, 2021). "It has been reported that TNF-α plays a role in promoting alcohol-induced osteoporosis." (PMID 34745415, 2021). "Serum immunomodulatory factors IL-6 and TNF-α can aggravate osteoporosis." (PMID 32670052, 2020). "Thus, new therapeutic strategies are urgently needed to efficiently repress TNF-α-induced cytotoxicity and apoptosis for the treatment of osteoporosis." (PMID 32400849, 2020). "Importantly, here we have found that IOs but only in combination with MF can significantly diminish expression of TNF-a, a cytokine which contributes to osteoporosis by triggering RANKL-induced osteoclast formation." (PMID 32070362, 2020).
osteoporosis (continued). "Cytokines and chemokines such as TNF-α, CCL-2, IL-10, SERT (Serotonin Transporter) and Tph1 may be possible mediators between the GM and steroid deficiency-induced osteoporosis." (PMID 32484785, 2020). "In vitro studies showed that genistein or daidzein could decrease bone resorption and promote bone formation by regulating the expression of OPG and RANKL as well as suppressing TNF-α and IL-6, so as to prevent osteoporosis." (PMID 33447176, 2020). "However, chronically elevated levels of TNF-α contribute to a myriad of inflammatory-related diseases including diabetes and osteoporosis." (PMID 33007863, 2020). "The mean of TNF-α also increased from normal group to osteoporosis group." (PMID 32704255, 2020). "Although TNF, IL-1, and IL-6 play an important role in the activation and differentiation of osteoclasts, current studies have not fully confirmed the role of proinflammation in the pathogenesis of osteoporosis." (PMID 32509864, 2020). "Osteoporosis is also considered a chronic inflammatory disease, as several increased proinflammatory cytokines, including tumor necrosis factor (TNF-α), interleukin (IL)-1β, and IL-6, may regulate RANKL expression." (PMID 32477149, 2020). "EXD ameliorated osteoporosis and reduced TNF-α level in OVX rats in the dose range of 2–6 g/kg/day." (PMID 31551787, 2019). "As is well known, estrogen plays a protective role in the development of osteoporosis, indirectly inhibiting osteoclast activity through the down-regulation of pro-inflammatory cytokines (IL-1, IL-6, TNF-α, M-CSF) and the up-regulation of TGF-ß, an inhibitor of bone resorption." (PMID 31540048, 2019). "Combining network pharmacology analysis with experimental verification in vivo and in vitro, we found that EXD may attenuate osteoporosis at least partially by reducing TNF-α production and regulating the Akt/Nrf2/HO-1 signaling pathway." (PMID 31551787, 2019). "For inflammatory diseases, bisphosphonates may be chosen as therapy, however specific medications such as denosumab, IL-1 receptor antagonists, or TNF-α antibodies are targeted treatment strategies for osteoporosis secondary to inflammation." (PMID 31795299, 2019). "Furthermore, IL-6 and TNF-α levels were also correlated with DANCR expression in low-BMD osteoporosis patients." (PMID 30937214, 2019). "Moreover, the allelic variants of the TNF-α gene and BMD, including those between SNPs rs1800630 (-863C/A) and rs1800630 (-1031T/C) of the TNF-α gene and low BMD are associated to a dinucleotide repeat polymorphism in TNF-α for linkage to osteoporosis." (PMID 31887189, 2019). "Among the pathological factors contributing to the frequent incidence of osteoporosis, increased secretion of pro-inflammatory cytokines such as interleukin (IL)-1, IL-6, IL-17, and tumor necrosis factor-alpha (TNF-α) suggests an intimate relationship between inflammation and osteoporosis 1-3." (PMID 31595160, 2019). "In addition, inflammation is closely related to osteoporosis, in which IL-1β, TNF-α, and IL-6 can activate the macrophages of the NF-κB pathway, thereby causing them to differentiate into osteoclasts." (PMID 31470845, 2019). "Several mechanisms are known to contribute to the pathology of menopause-induced primary osteoporosis such as increased expression of tumour necrosis factor (TNF) superfamily members TNFα (TNFSF2) and receptor activator of nuclear factor kappa-B ligand (RANKL; TNFSF11)." (PMID 31299941, 2019). "Prior studies found that the SNPs in TNF-α gene are related to osteoporosis in elderly people." (PMID 31887189, 2019). "Additionally this study demonstrated that the T-cells of osteoporosis patients play a key role in the osteoclastogenesis by increasing the TNF-α and RANKL production." (PMID 30941138, 2019).
osteoporosis (continued). "The connection between inflammation and bone metabolism has been further evidenced in different animal models of osteoporosis where the deletion of the receptor for key inflammatory cytokines, like interleukin-1 (IL1) and tumor necrosis factor (TNFα), dramatically reduced the bone loss." (PMID 29867550, 2018). "Despite the fact that the expression levels of IL-10 and IL-17α in the colon were impacted in a way that has been shown to favor the development of osteoporosis (32, –, 34), serum levels of TNF-α and T cell populations in the bone marrow compartment were not impacted by the presence of a microbiota." (PMID 29299532, 2018). "It is known that TNF-α blocks osteoblast differentiation and stimulates osteoclast formation, and results in impaired new bone deposition, and accelerated bone resorption, especially in conditions like inflammatory bone diseases and osteoporosis." (PMID 29484117, 2018). "The fact that these mice develop osteoporosis suggests that TNFα overproduction may play a major role in the development of this condition since TSH has been shown to directly downregulate TNFα transcription induced by IL1 or RANKL treatments." (PMID 29042858, 2017). "The pathogenesis of osteoporosis in chronic inflammatory disease may be secondary to releases of cytokines such as TNF- and IL6." (PMID 26221501, 2015). "Furthermore in another study, Sr-Ca coadministration resulted in decreased expression of TNF-α in large animal model of osteoporosis." (PMID 27355060, 2014). "LPva may inhibit inflammation that may be responsible for osteoporosis by inhibiting tumor necrosis factor (TNF)-α production and down-regulating cyclooxygenase-2 expression." (PMID 24007208, 2013). "In addition, post-menopausal condition can stimulate the formation of osteoclast by the production of nuclear factor-kβ ligand (RANKL) and tumor necrosis factor (TNF) by monocytes and T cell, and this phenomenon tends to occur in women with osteoporosis." (PMID 23800238, 2013). "As we observed increased levels of both IL-1β and TNF-α in P2X7MUT subjects relative to P2X7WT subjects, it might be suggested that P2X7MUT subjects have an increased risk to develop osteoporosis." (PMID 23210974, 2012). "IL-1β, IL-6, TNF-α, and the osteoporosis-related protein system OPG/RANK/RANKL may have some synergetic effects on emphysema and bone loss in COPD." (PMID 22176920, 2011). "Experimental studies indicate that IL-1β, IL-6 and TNF-α may play important roles in the etiology of both osteoporosis and emphysema." (PMID 22176920, 2011). "However, it is unclear whether miR‐27a‐3p functions as a downstream regulator of inflammatory signals and participates in the TNF‐α‐mediated osteoporosis." (PMID 38748896, 2024). "In accord with these findings, several studies recently suggested that inhibition of TNF‐α‐mediated impairments in osteogenesis, such as using resveratrol, quercetin and artemisinin, can help to promote the osteogenesis of mesenchymal stem cells thereby potentially improved osteoporosis." (PMID 38748896, 2024). "Also, NLRC3 attenuates TNFα+ Th17 cell accumulation into the bone marrow in osteoporosis." (PMID 38436712, 2024). "However, increased TNF-α in osteoporosis patients had been reported." (PMID 39703374, 2024). "Furthermore, CTSK, CSF1, TNFSF11, CTNNB1, TNFRSF11A, and TNF may be the most promising osteoporosis markers." (PMID 37893075, 2023). "Therefore, it can be seen that TNF-α and IL-6 may affect osteoclast function and lead to osteoporosis through the OPG/RANK/RANKL axis." (PMID 38041076, 2023). "Moreover, TNF-alpha contributes to osteoporosis, promoting RANKL-induced osteoclast formation." (PMID 36506070, 2022). "In addition, to investigate whether HUCWJCs affect the progression of osteoporosis through inflammation, TNFα, one of the major inflammatory factors, was included in our study." (PMID 35936064, 2022).
osteoporosis (continued). "It has been proven that oxidative stress influences inflammatory cytokines like TNF‐α or interleukins, which orchestrated synergy plays a key role during intercellular redox state, leading to important alterations of the differentiation process and osteoporosis development." (PMID 34075722, 2021). "However, the treatment of anti-TNF-α significantly alleviated OVX-induced osteoporosis." (PMID 33425899, 2020). "Cytokines other than RANKL and OPG, such as interleukin (IL)-1α, IL-6 and tumor necrosis factor-α, that are largely recognised as important effectors in the pathogenesis of several forms of osteoporosis, could have a role in TM-related osteoporosis." (PMID 29991466, 2019). "The combination of MAP infection, known to induce production of TNFα, and presence of defective T-cells in RA should lead to excessive elevation of inflammatory markers, which ultimately should impact osteoclastic activity and possibly development of osteoporosis." (PMID 31817071, 2019). "When studying NR_024031, also named DANCR, researchers found that DANCR promoted the expression of IL-6 and TNF-α, and DANCR-induced IL-6 and TNF-α had bone-resorbing activity indicating that DANCR is involved in the pathology of osteoporosis and may be a biomarker for postmenopausal osteoporosis." (PMID 28173844, 2017). "For instance, augmented levels of pro-inflammatory cytokines like TNF-α and RANKL in osteoporosis patients enhance TRAF6 and MAPK activation, promoting osteoclast activity and leading to bone loss." (PMID 40496246, 2025). "Inflammatory mediators such as tumor necrosis factor-alpha (TNF-α), interleukin-1 beta (IL-1β), and interleukin-6 (IL-6), which are elevated in both osteoporosis and neurodegenerative diseases, serve as common mechanistic links." (PMID 41007423, 2025). "In osteoporosis, TRAF2 is thought to inhibit BMP signaling as TNF-α exposure results in decreased phospho-Smad1, BMPR-IA, and Runx2 levels, while BMPR-IB and BMPR-II levels increase." (PMID 40496246, 2025). "Conversely, the Swiss registry suggests that early anti-TNF-α treatment (<24 months after diagnosis) significantly reduces the risks of low BMD and osteoporosis after a 10-year follow-up (11.4% vs. 28.2%, p < 0.001)." (PMID 40364233, 2025). "TNF-α and RANKL promote osteoclast differentiation by activating RANK-involved NF-κB signaling, ultimately leading to osteoporosis." (PMID 40284791, 2025). "Pro-inflammatory cytokines such as interleukin-1 and tumor necrosis factor-α (TNF-α) induce COX and nitric oxide synthase to release PGs and NO, contributing to osteoporosis development." (PMID 39773558, 2025). "Studies have reported that venom extracts from certain scorpions can restore serum levels of serum ALP, TRAP, PTH, osteocalcin, TNF-α, and bone minerals in OVX rats, combatting osteoporosis and enhancing BMD." (PMID 41208866, 2025). "During estrogen deficiency, the activation of IL-17 significantly contributes to osteoporosis by increasing the secretion of RANKL, TNF-α, and IL-1 and IL-6, promoting bone resorption." (PMID 40496246, 2025). "Curculigoside is likely to treat osteoporosis through targets such as MMP3, MMP9, IL-6, and caspase-3, acting on signaling pathways including Rap1 and TNF." (PMID 40917365, 2025). "The results demonstrate that resveratrol improved TNF-α–inhibited osteogenic differentiation of MSC, contributing to slowing osteoporosis progression." (PMID 41226117, 2025). "Elevated TNF-α levels in postmenopausal women are known to accelerate RANKL-induced osteoclast formation, contributing to osteoporosis." (PMID 40284791, 2025). "Resveratrol promotes osteogenic differentiation by inhibiting apoptosis and regulating apoptosis-related proteins such as TNF and IL6, with potential implications for osteoporosis treatment." (PMID 40243497, 2025). "This study aimed to explore the correlation between TNF‐α treatment and miR‐27a‐3p expression in BMSC osteogenesis and further understand their roles in osteoporosis." (PMID 38748896, 2024).